ENSG00000252433
Synonyms: LOC124900434
Gene: Small nucleolar RNA gene on chromosome 1 (67,102,645 to 67,102,779, reverse strand). Ensembl gene ENSG00000252433.
Gene Ontology:
Biological process: RNA processing
Cellular component: nucleolus
Homologues: Orthologues: rat LOC120102627 (73% identical). Paralogues in human: SNORA31B (86% identical), SNORA31 (67% identical).